CSF1R (colony stimulating factor 1 receptor)
Diseases named in the same sentence as CSF1R in open-access papers (continued):
Sharing a sentence is not in itself a finding about the gene and the disease.
tumor (continued). "This triple therapy significantly increased the survival of GL261 tumor bearing mice when compared to non-treated, DC vaccinated and DC vaccinated mice with either CSF-1R or PD-1 blockade alone." (PMID 33178210, 2020). "Inhibition of CSF-1R by TAS-115 may suppress the polarization into M2 macrophages that depends on CSF-1 signaling, which promotes tumor growth, invasion, and metastasis, and thus, the immune environment in tumors may be improved." (PMID 31820255, 2020). "Moreover, targeting immunosuppressive TAM alone with a CSF-1R inhibitor increased allogeneic CD8+ T-cellinfiltration in the tumor, however alone it still yielded a limited effect on tumor apoptosis consistent with previous studies." (PMID 32909947, 2020). "In the murine MM model, a CSF1R inhibitor demonstrates a therapeutic effect against cancer by repolarizing MAMs to adopt an M1-like phenotype and inducing a cytotoxic CD4+ T-cell response against tumor cells." (PMID 32801364, 2020). "In lung squamous cell carcinoma, stromal macrophages, activated through CSF-1R (the receptor of colony-stimulating factor-1 (CSF-1), a macrophage growth factor), trap CD8+ T cells and prevent them from entering the tumor core, thereby limiting the efficacy of PD-1 blockade therapy." (PMID 32457745, 2020). "For instance, using different mouse tumour models, Kumar and colleagues demonstrated that CSF1-R is not only expressed on macrophages, but also on CAFs." (PMID 31331034, 2019). "The utility of CSF1R inhibitors and ICIs in CRC, a tumor-type in which CSF1R-positive TAMs predominate and mediate an immunosuppressive tumor milieu, is currently under investigation in multiple early-phase studies (i.e., NCT02777710, NCT02452424, NCT02829723, NCT02880371)." (PMID 30654522, 2019). "CSF-1R blockade delayed tumor growth by shifting the polarization rather than the depletion of TAMs." (PMID 31572568, 2019). "Nevertheless, additional studies are needed to understand macrophage heterogeneity and function within the tumor microenvironment as well as how selective blockade of CSF1, IL34, or CSF1R and subsequent effects on TAMs correspond with response to checkpoint blockade." (PMID 31552020, 2019). "Mechanistically, CSF-1R inhibition mediated the reprogramming of TAMs toward an anti-tumorigenic phenotype, without depleting cells within the tumor bulk." (PMID 31611871, 2019). "The combination of anti-CD40 plus anti-CSF-1R antibodies has been evaluated in “cold” preclinical tumor models, not responsive to ICB." (PMID 31878087, 2019). "In contrast, 3D185 was inactive against 20 additional tumor cell lines that exhibited low expression or activation of FGFR and CSF-1R (IC50 > 1 μM), further demonstrating that 3D185 is a highly potent and selective FGFR1/2/3 and CSF-1R inhibitor." (PMID 31438996, 2019). "Thus, combinatorial therapy targeting both CSF1R and CXCR2 seems to have more chances to generate an effective anti-tumor T cell response." (PMID 31447834, 2019). "In mouse models of solid tumors including colon cancer, breast cancer, and glioblastoma, monoclonal antibodies or small molecule inhibitors against CSF1R reduces the number of TAM and/or changes the phenotype of TAM, which impairs tumor development and progression." (PMID 29670880, 2018). "Given the effects of CSF-1R expression on the human PDAC tumor immune microenvironment after receiving GVAX, we hypothesized that the addition of anti-CSF-1R antibody (αCSF-1R) to GVAX and anti-PD-1 antibody (αPD-1) could further improve survival outcomes." (PMID 30424804, 2018).
tumor (continued). "Also, in a pancreatic cancer mouse model, the combination of depleting M2-like TAMs and repolarization towards antitumoral behavior through blockage of CSF-1/CSF-1R and immunotherapy (PD-1 and CTLA-4 antagonists) reduced tumor progression." (PMID 30410942, 2018). "We propose that the addition of anti-CSF-1R antibody to the combination of GVAX therapy and anti-PD-1 antibody can improve the survival outcome of PDAC by further altering the myeloid population and creating a more anti-tumor immune environment." (PMID 30424804, 2018). "Unfortunately, in our experiments the CSF1R inhibitor BLZ-945 did not prevent macrophage-induced tumor cell budding, nor did it induce tumor cell killing (KT, unpublished results)." (PMID 29731961, 2018). "TAMs are known to have a role in tumor angiogenesis; therefore, we assumed that TAMs can affect the increase in nCBV values, which can be simultaneously correlated with TAM markers (e.g., CD11b, CD68 and CSF1R)." (PMID 30375429, 2018). "These alterations, alongside the cytokines and growth factors released by macrophages that will be lacking following CSF1R inhibition, result in reduced tumor cell proliferation and changes in a number of tumor cell intrinsic pathways (MYC, metabolism)." (PMID 29719257, 2018). "In addition, significant synergy was observed combining CSF1R inhibitors with idelalisib or ibrutinib, two current CLL therapies that disrupt tumor cell intrinsic B-cell receptor signaling." (PMID 29872489, 2018). "Furthermore, we discuss the local tissue macrophage and tumor-type specificities and their potential impact on CSF1/CSF1R-targeting treatment strategies for the future." (PMID 28716061, 2017). "On the other hand, lack of Nur77 results in low levels of CSF-1R expression, which reduces the migratory capacity of inflammatory cells and subsequently hinders cell chemotaxis and tumor infiltration." (PMID 28170411, 2017). "Because recruitment of TAMs to target vessels to induce vascular permeability requires CCL2 and colony-stimulating factor 1 (CSF1) synthesized by tumor cells to target receptor CCR2 and CSF1R on TAMs, inhibition of CCR2 or CSF1R signaling reduces tumor growth and metastasis." (PMID 28467800, 2017). "Mice treated with a CSF1R inhibitor (AC708) after anti-VEGF antibody resistance had little to no measurable tumor burden upon completion of the experiment while those that did not receive a CSF1R inhibitor still had abundant tumor." (PMID 29228548, 2017). "For instance, in case of CSF1R, the humanised monoclonal antibody RG7155 potently inhibited CSF1R dimerisation and also induced a striking reduction in the CSF1R+CD163+ macrophage population within tumour tissues." (PMID 29065107, 2017). "Importantly, CSF-1R blockade in combination with antibody against PD-1 or CTLA-4, in addition to gemcitabine, led to strengthened tumor regression." (PMID 29299180, 2017). "In addition, targeting TAMs with anti-colony-stimulating factor 1 receptor (CSF-1R) monoclonal antibody RG7155 resulted in depletion of TAMs and objective response of the tumor." (PMID 27144518, 2016). "Mechanistic studies revealed that DNA damage-induced kinase ABL1 enhanced CSF-1 expression, while selective inhibition of its receptor kinase CSF1R (CD115) by GW2850 or PLX3397 inhibitors hampered TAM recruitment and suppressed tumor growth in murine prostate and thyroid cancer models." (PMID 27886105, 2016). "CSF-1 receptor (CSF-1R) signaling is currently under investigation as a therapeutic target and we have identified CSF-1-stimulated macrophage motility, through PI3K p110δ and SFKs, as a promising specific target to prevent tumor invasion." (PMID 31453214, 2016). "To test our hypothesis that BMM motility regulates tumor cell invasion, we compared the effects of an inhibitor of PI3K p110δ, GS-1101, that blocks macrophage motility with a CSF-1R inhibitor, GW2580, in our mammosphere co-culture model." (PMID 31453214, 2016).
tumor (continued). "In order to investigate whether myeloid cells participate in the elimination of tumor cells in vivo, we treated TC1-tumor bearing mice with the compound vaccine and PLX3397, a CSF1-R signaling inhibitor." (PMID 26337837, 2015). "Treatment with a colony-stimulating factor-1 receptor (CSF1R) inhibitor similar to the ones currently in clinical trial to block MDSCs also blocked monocyte and moDC accumulation in the dLN, as well as tumor-specific T cell proliferation in dLN and antitumor activity." (PMID 26635798, 2015). "Positivity of CSF1R immunostaining was not statistically correlated with the number of giant cells, tumor volume, gender, age, or tumor localization." (PMID 25854167, 2015). "The distal segment contains the elements required for growth factor-inducible expression of reporter genes in non-macrophage tumour cell lines, including signaling by ectopically-expressed CSF1R." (PMID 25137049, 2014). "In some, but not all, of these tumor models, there was also an increased population of neutrophils expressing CSF1-R (CD115)." (PMID 23423530, 2013). "We previously provided evidence that the Csf1r proximal promoter was active in non-macrophage tumour cells, and was growth factor-responsive." (PMID 23383005, 2013). "We have also shown in the past that CSF-1R is expressed in all macrophages and PyMT tumor cells do not express the CSF-1 receptor (CSF-1R) and this was confirmed in the primary isolates of tumor cells used in these experiments by RT-PCR (data not shown)." (PMID 19668347, 2009). "We observed no increase in the transmigration of tumor cells seeded with Csf1r−/− macrophages compared to tumor cells cultured without macrophages; however, tumor cell trans-endothelial migration was enhanced when seeded with macrophages expressing the CSF-1R (Csf1r+/+)." (PMID 40646332, 2025). "This suggests that the cellular composition of the tumor microenvironment, rather than ligand expression alone, may influence the efficacy of CSF1R blockade." (PMID 40643554, 2025). "Intra- and inter-tumor heterogeneity or the lack of biomarkers that could predict the rate of response to CSF1R inhibitors are potential reasons for such discrepancies in the outcomes observed in clinical trials." (PMID 40538439, 2025). "Anti-CSF1R therapy may not be sufficient to deplete all tumor-promoting SPP1+ macrophages, which may contribute to the poor efficacy of anti-CSF1R monotherapy in the Renca mouse tumor model and human cancer patients." (PMID 40092488, 2025). "However, current macrophage depletion strategies such as clodronate liposomes or CSF1R inhibitors result in only partial depletion, and while they improve tumor control by radiation they are not curative therapies in preclinical models." (PMID 41417245, 2025). "Whether this reveals different effects of inhibiting CSF-1R compared with decreasing CSF-1 in the tumor, or whether the lack of IGF-1 upregulation reflects a limitation of our athymic model due to lack of T-cell signaling, remains to be investigated." (PMID 40844085, 2025). "Non-tumor components included endothelial cells (expressing VWF, CDH5, ECSCR, SLCO2A1, and MYCT1), pericytes (marked by RGS5, MCAM, and PDGFRB), normal oligodendrocytes (showing PTGDS, MBP, TF, and MOG expression), and TAMs (identified by CD14, AIF1, FCER1G, FCGR3A, TYROBP, and CSF1R)." (PMID 41394801, 2025). "It includes CD40 agonists, CSF-1R inhibitors, CD11b agonists, CCR2 inhibitors, BTK inhibitors, and emerging chemokine receptor inhibitors, such as CXCR2 and CXCR4 antagonists, highlighting the diverse immune modulating approaches to reprogram the immunosuppressive tumor microenvironment." (PMID 40458409, 2025). "In this study, we demonstrate that inhibition of CSF-1R signaling in vitro by either knocking out CSF-1R in macrophages, or adding a blocking antibody, decreased macrophage release of VEGF-A, as well as trans-endothelial migration of tumor cells, an in vitro measure of intravasation capability." (PMID 40646332, 2025).
tumor (continued). "RT-qPCR analysis showed low absolute expression levels of CSF1R in tumor cells but high expression levels in the macrophage cell line RAW264.7, indicating that macrophages might be the main target of irradiated tumor cell-derived MCSF." (PMID 39165639, 2024). "Using a CSF-1R blocker (Pexidartinib), in the form of hydrogel loaded with Pexidartinib (PLX)-encapsulated nanoparticles, facilitates the local and systemic delivery of anti-programmed cell death protein 1 (anti-PD-1) antibody-conjugated platelets and inhibits tumor recurrence after surgery." (PMID 39796695, 2024). "Tumor cells initiate recruitment of monocyte-derived circulating macrophages by production of Colony Stimulating Factor 1 (CSF1) and CC chemokine Ligand 2 (CCL2), leading to their binding to CSF1 receptor (CSF1R) and CCL2 receptor (CCR2) on the macrophage cell surface." (PMID 39660126, 2024). "Within these proteins, we considered IRAK1 and CSF1R as potential pharmacological targets for the treatment of LUAD, based on previous research indicating they could be targeted by FDA-approved drugs, though in other tumor types." (PMID 38182978, 2024). "For example, the highly specific CSF-1R tyrosine kinase inhibitor, PLX3397, has been shown to repolarise TAMs to a more proinflammatory phenotype, as well as inhibit macrophage proliferation and increase cytotoxic T-cell tumour infiltration in HCC tumours in mice." (PMID 39684877, 2024). "Blocking this pathway with the CSF1-R inhibitor PLX3397, or GW2580 significantly reduced both the proportion of M2 macrophages and the total number of TAMs, thereby allowing M1 macrophages to become the predominant component of TAMs and exert anti-tumor efficacy." (PMID 39175095, 2024). "Both IL-34 and CSF1, which are ligands for CSF1R, are known chemotactic factors for circulating monocytes secreted by SCs, and previous work has shown that both IL-34 and CSF1 are expressed in VSs, with a weak correlation between tumor growth and CSF1 levels described." (PMID 38216553, 2024). "Besides, elevated expression of CSF1R leads to increased lactate levels in HNSCC, reduces the presence of tumor-infiltrating macrophages, and promotes the induction of M2-like macrophage polarization within the tumor." (PMID 38650924, 2024). "Additionally, in situ hybridization analysis in a set of LMS cases demonstrated that LMS cells produced both CSF-1 and CSF-1R, while macrophages did not secrete CSF-1, indicating an autocrine receptor activation at the tumor cell membrane." (PMID 38254773, 2024). "The concurrent targeting of TAMs through a combination of a CSF1R inhibitor and cisplatin diminished Tregs, redirected the function of PD-1 antibodies toward CD8+ T cells, and bolstered the efficacy of antiangiogenic immunotherapy, resulting in significant tumor regression." (PMID 38044943, 2023). "Other preclinical studies have revealed possible mechanisms that might explain why CSF1R blockade therapy fails, including an influx of regulatory T-cells, tumor-promoting granulocytes, TAMs resistant to CSF1R and aberrant signaling of PI3K that is downstream of CSF1R signaling." (PMID 37964379, 2023). "In this study, CSF1R antibody or PLX3397 treatment could inhibit the macrophages ratio in the tumor, but this treatment could not completely delete TAM." (PMID 36969873, 2023). "Hence, targeting the CSF1/CSF1R could potentially decrease MDSC expansion and activity in the 4T1 tumor model, resulting in enhanced efficacy of therapeutic cancer vaccines." (PMID 37505292, 2023). "Similarly, anti-CSF1R treatment reduced tumor growth and tumor weight in Aurkafl/fl;Cd19cre/+ mice but not in Aurkafl/fl mice." (PMID 37064877, 2023). "Moreover, CCR2 and CSF1R surface proteins of MφNP may interact with CCL2 and CSF1, respectively, which are known for recruiting monocytes and macrophages into the tumor tissue." (PMID 38111068, 2023).
tumor (continued). "In contrast, substances that hinder M2 polarization, such as CSF1R inhibitors, corosolic acid, omeprazole, Gpr132 inhibitors, MEK/STAT3 inhibitors, fast-mimicking diets, and antibodies against IL-4, IL-4Rα, and IL-13, are also able to diminish the amount of tumor burden." (PMID 37211559, 2023). "At both the primary tumor and the metastatic site, glufosinate rewires macrophages towards an M1-like phenotype, countering immunosuppression and stimulating vascular sprouting, however, TAM elimination by anti-CSF1R substantially neutralized glufosinate effects on metastasis." (PMID 37426676, 2023). "CSF1R inhibitors as monotherapy does not always inhibit tumor growth in some cancer treatment studies, which may be due to individual heterogeneity, immune environment differences and different tumor stages." (PMID 36969873, 2023). "Regorafenib is an oral inhibitor of several kinases involved in tumor angiogenesis (VEGFR1-3 and TIE2), oncogenesis (KIT, RET, RAF1, and BRAF), and in the interaction between tumor and microenvironment (PDGFR, FGFR), and tumor immunity (colony-stimulating factor 1 receptor [CSF1R])." (PMID 37071295, 2023). "This causes overexpression of CSF1, responsible for the recruitment and growth of CSF1R expressing monocytes and drives the development of a tumor formed by a large number of nonneoplastic macrophages expressing CSF1R and a minority of neoplastic cells, which do not express CSF1R." (PMID 37546427, 2023). "We hypothesized that targeting MDSCs by inhibiting the CSF-1R axis could hinder the M-MSDCs recruitment and activate the immunity in the tumor microenvironment when combined with BNCT, leading to a synergistic effect for better tumor control." (PMID 37886177, 2023). "Interestingly, timing of CSF-1R inhibition can impact anti-tumor response with earlier treatment being more effective, likely due to the distribution of TAM subsets at different stages of tumor development." (PMID 35821822, 2022). "We thus hypothesized that a) CSF1R+ M2 macrophages enhance experimental MPE formation, mainly by modulating the immune tumor/pleural microenvironment to promote angiogenesis and vessel permeability and b) that CSF1R inhibition would effectively limit MPE formation." (PMID 35315360, 2022). "However, depletion of CSF-1R+CD11c+ cells with the CSF-1R inhibitor PLX3397 in combination with αPD1 only induced a tumor growth delay and was not able to eliminate the tumors." (PMID 35292516, 2022). "However, another possibility is that CSF-1R inhibition targeted “earlier” TAM populations, minimizing the transition of these cells to mature F4/80high TAMs and therefore reducing their proportion in the tumor." (PMID 35821822, 2022). "Sulfatinib is a small molecule tyrosine kinase inhibitor that targets tumor angiogenesis and immune modulation, inhibiting vascular endothelial growth factor receptors (VEGFRs) 1, 2, and 3, the fibroblast growth factor receptor type 1 (FGFR1), and colony-stimulating factor 1 receptor (CSF-1R)." (PMID 35897702, 2022). "Administration of anti-CSF1R antibody failed to significantly alter tumor growth or change the CTL infiltration, despite a pronounced decrease in the average frequency of tumor-infiltrating F4/80hi TAMs by 61% in YUMM3.3-Ctrl, or by 86% in -βΑ tumors, respectively." (PMID 35580932, 2022). "While CSF-1R has been repeatedly used as a macrophage marker in normal tissues, recent studies suggested that blockade of CSF-1R does not abolish macrophage population in tumor tissues but alters macrophage polarization instead." (PMID 35444953, 2022). "Consistent with previous publications, anti-CSF1R monotherapy failed to inhibit tumor growth." (PMID 35179953, 2022). "Furthermore, mononuclear phagocytes are the primary mediators of ADCP and so their elimination at tumor sites does not make anti-CSF-1R mAb blockade an attractive strategy to combine with established direct targeting mAbs." (PMID 34638388, 2021).